MUC1 (mucin 1, cell surface associated)
Diseases named in the same sentence as MUC1 in open-access papers (continued):
Sharing a sentence is not in itself a finding about the gene and the disease.
tumor (continued). "Only one study has investigated the association of postoperative MUC1 assessments in relation to other prognostic factors (tumor size, lymph-node status, histological grading, and hormone receptor status)." (PMID 35406491, 2022). "Increased expression of mucin MUC1 has been linked to tumor aggressiveness and autophagy-mediated chemotherapy resistance as reported using the MCF7 cell line model." (PMID 35290621, 2022). "MUC1 has been implicated in various aspects of tumor biology including cell proliferation, migration and cancer drug resistance." (PMID 36430448, 2022). "Such differential expression of MUC1 has been associated with tumor cell proliferation, migration, invasion, adhesion, and metastasis." (PMID 36359337, 2022). "Tumor-associated MUC1 (tMUC1) is different from the MUC1 expressed in normal cells and can be used as a biomarker and therapeutic target of cancer." (PMID 36497465, 2022). "As a consequence, tumour-associated MUC1 exposes aberrant tumour-associated carbohydrate antigens (TACAs) in combination with the normal antigens." (PMID 35351156, 2022). "The obtained results show that immunization with recombinant chimeric NoV VP1- MUC1 VLPs result in high titers of MUC1 specific IgG antibodies and show great therapeutic potential as a platform to present tumour-associated antigens." (PMID 35351156, 2022). "Tumour-associated MUC1 is ubiquitously overexpressed, hypoglycosylated, and secreted as soluble glycoforms (e.g. CA 15-3 or CA27.29) by epithelial adenocarcinomas, including those of the breast, ovary, colon, and lung." (PMID 36307410, 2022). "The National Cancer Institute (NCI) ranks MUC1 second on its list of 75 tumor-associated antigens, based on criteria such as therapeutic function, immunogenicity, specificity, and carcinogenicity." (PMID 35891256, 2022). "In RCC patients, MUC1 expression is positively associated with tumor progression and nuclear grade, and is inversely correlated with patient survival." (PMID 35054482, 2022). "Pankomab, an antibody targeting this carbohydrate-induced conformational tumor-associated epitope on MUC1, features the highest glycosylation dependency and strongest additive binding effect compared to past MUC1 antibodies." (PMID 35522218, 2022). "MUC1, an integral membrane protein, is overexpressed in 90% of adenocarcinomas and has been linked to tumor aggressiveness." (PMID 35265667, 2022). "This becomes more important considering that tumor‐associated MUC1 is usually expressed in higher levels during carcinomas and is in its hypo‐glycosylated form." (PMID 34694686, 2022). "Mucin 1 (MUC1), a well-known tumor-associated antigen and attractive target for tumor immunotherapy, is overexpressed in most human epithelial adenomas with aberrant glycosylation." (PMID 35186882, 2022). "Underscoring these results, analysis of bulk RNA-seq TNBC tumor datasets demonstrated that MUC1 expression significantly associates with expression of IRDS genes." (PMID 35681561, 2022). "Tumour-associated MUC1 differs from that expressed in healthy cells by presenting increased sialylation and loss of core 1 O-glycans and abnormal cellular distribution." (PMID 34452200, 2021). "Both univariate and multivariate analysis revealed that the protein expression of MUC1 was associated with overall survival and relapse-free survival after tumor resection." (PMID 34729096, 2021). "MUC1-rs4072037 is an independent risk factor that influences tumor recurrence and disease-related death in diffuse-type gastric cancer, but not in intestinal-type gastric cancer." (PMID 34771687, 2021). "Upregulation of MUC1 and MUC4 was also identified in uninvolved colon in IBD, and changes in glycosylation of MUC1 have been implicated in IBD-associated neoplasia." (PMID 34333236, 2021).
tumor (continued). "A rise in glucose uptake can make tumor tissues less sensitive to increased drug concentrations; MUC1 amplifies this phenomenon, making it inextricably linked to drug resistance in tumors." (PMID 34207342, 2021). "Single-cell scRNA-seq datasets of TNBC samples were analyzed for normalized expression associations between MUC1 and selected genes within tumor cells." (PMID 33495298, 2021). "On many epithelial-origin cancer cells, MUC1 is enriched by specific tumor-associated carbohydrate antigens (TACAs), including Tn, T, sTn, and sT sugar structures." (PMID 34206951, 2021). "Modified DC (gmDC) vaccine: The adenovirus (Ad-siSSF) delivers two tumor-associated antigens (TAAs), survivin and MUC1; secretory bacterial flagellin for DC maturation; and an RNA interference moiety to suppress SOCS1." (PMID 33937323, 2021). "The cell surface expression levels of under-glycosylated, cancer-associated MUC1 are reduced compared with normal MUC1, either due to decreased delivery to the cell membrane or due to faster endocytosis, a critical tumor immune escape mechanism." (PMID 34070311, 2021). "NPs have been developed to deliver mRNA vaccines that encode the tumor antigen MUC1 to DCs in lymph nodes, thereby facilitating the activation and expansion of tumor-specific T cells." (PMID 34207342, 2021). "Several tumour-associated antigens (TAAs) have been identified as promising targets for cancer immunotherapy, including mucin-1 (MUC1) and survivin." (PMID 34066318, 2021). "MUC1 had been found to engage with Siglec‐9, induced tumor‐associated macrophage‐like phenotype, and increased PD‐L1 expression in the tumor microenvironment." (PMID 34327857, 2021). "In order to allow delivery of two tumour-associated antigens concurrently, the MUC1 peptide SAPDT(GalNAc)RPAPGST(GalNAc)APPA was conjugated onto surv.VLP via an intracellular reducible linker." (PMID 34066318, 2021). "As was mentioned in the Introduction section, tumor-associated MUC1 plays a crucial role in the development of many cancers." (PMID 34206951, 2021). "Nevertheless, there are preclinical and clinical trials assessing anti-tumour-associated MUC1 agents in ovarian carcinomas." (PMID 34830751, 2021). "The first is a vaccine that uses MUC1 alongside tumor-associated carbohydrate antigens (TACAs), such as Tn and STn, with variable number tandem repeats (VNTRs) as immunogens." (PMID 34207342, 2021). "Higher expression of tumour-associated MUC1 has been linked to micro-metastasis formation, where it functions as an anti-adhesion molecule, allowing for the migration of tumour cells." (PMID 34830751, 2021). "Likely, because of its size, density of O-linked glycosylation, and high-expression levels in many tumors, aberrantly glycosylated MUC1 is an attractive tumor-associated antigen for immunotherapy." (PMID 34640530, 2021). "MUC1 with modified glycan side chains can serve as a tumor-associated antigen to elicit MUC1-specific tumor immunotherapy and serve as a valid target for immunotherapy." (PMID 34572503, 2021). "Our previous studies have shown that circulating PNA mimics the actions of endogenous galactoside-binding protein galectin-3 by interaction with tumour cell-associated MUC1 and promotes circulating tumour cell metastatic spreading." (PMID 34223877, 2021). "We confirmed that these antibodies specifically recognize tumor-associated MUC1 epitopes and can activate human NK cells in vitro." (PMID 34070311, 2021).
tumor (continued). "MUC1 high expression in advanced PCa is associated with adverse clinicopathological tumour features and poor outcomes." (PMID 33509203, 2021). "Two tumor-associated proteins MUC1 and EpCAM exhibit a highly positive correlation, thereby suggesting a consistent role in cancer metastatic progression." (PMID 34099708, 2021). "We observed a statistically significant increased expression in tumor samples for a majority of the genes encoding membrane-bound mucins (MUC1, -3A, 4, -12, -13, -16, -17, and -20) (p < 0.01)." (PMID 33182511, 2020). "We found that the sialylated tumour-associated glycoform of MUC1, MUC1-ST, bound to Siglec-9 expressed by monocytes and induced monocytes to secrete factors associated with tumour progression." (PMID 33149188, 2020). "The aberrantly glycosylated MUC1 expressed on malignant cells, called the tumor associated MUC1 or tMUC1 renders usually inaccessible MUC1 epitopes open to detection." (PMID 33167508, 2020). "The overexpression and aberrant expression of MUC1 have been linked to tumor aggressiveness and metastasis, poor response to therapy, and poor survival in several tumor types." (PMID 32429033, 2020). "Since AN people have a high prevalence of H. pylori infection, we evaluated the expression of MUC1 and the tumor-associated glycoform of MUC1 and detected the high expression of both in the majority of patients." (PMID 31941061, 2020). "The under-glycosylated (u) MUC1 or (tumor-associated) TA-MUC1 epitope, which becomes expressed on the entire cell surface." (PMID 33371487, 2020). "High MUC1 expression is detected in more than 60% of PC cases and is significantly associated with tumour size." (PMID 32745356, 2020). "Loss of transmembrane glycoprotein Muc1 results in significant delay in tumor progression and metastasis, consistent with delayed progression to malignancy displayed by PyMT/p11-KO tumors." (PMID 33297495, 2020). "sLea is overexpressed on a wide variety of tumor-associated glycoproteins, including mucin-1 (MUC1), MUC5AC, and MUC16 (CA125)." (PMID 33371487, 2020). "TAB004 distinguishes between normal and tumor-associated forms of MUC1 solely based on the expression of hypo-glycosylated or aberrantly glycosylated MUC1." (PMID 33167508, 2020). "Significant associations between MUC1 expression and methylation levels of cg14721139, cg11158374, cg12456510, cg26403416, cg18879389, and cg09410308 were identified in GC tumor sample (all P < 0.05)." (PMID 32122390, 2020). "Because of the aberrant glycosylation, T- and B-cell epitopes in the peptide backbone are now accessible, forming tumour-associated MUC1 antigens." (PMID 32377198, 2020). "In macrophages, binding of cancer-associated MUC-1 to Siglec-9 induced the conversion into the M2 phenotype, which has the function of reducing inflammation and contributing to tumor growth and immunosuppressive function." (PMID 32575400, 2020). "MUC1 protein in tumor cells or tumor-associated MUC1 (TA-MUC1) differs from MUC1 expressed in normal cells, with regard to its cellular distribution, biochemical features, and function." (PMID 32660489, 2020). "This difference in glycosylation state between the epitopes of MUC1 expressed by healthy and malignant tissues has been exploited to create several antibodies capable of specifically binding the tumor-associated antigen, including AR20.5." (PMID 32429033, 2020). "This approach caused production of more MUC1 specific antibody, that can bind to the MUC1 expressing tumor cells, in order to destroy them through antibody-dependent cell-mediated cytotoxicity (ADCC)." (PMID 32659971, 2020). "Little is known regarding the specifics of tumor-associated MUC1 (tMUC1) epitope, but thus far, tumor MUC1 targeting is mostly restricted to the VNTR region." (PMID 31178870, 2019). "Binding and pharmacokinetic properties of [89Zr]Zr-Df'-GGSK-1/30 were analyzed in vitro using human and murine cell lines that express tumor-associated MUC1." (PMID 31588183, 2019).
tumor (continued). "Altogether, these findings indicated that the MUC1 vaccine, indomethacin, and indomethacin + MUC1 vaccine treatments cause complex changes in gene expression and protein expression within the tumor microenvironment." (PMID 31693710, 2019). "Due to its tumor selectivity, the epitope of Gatipotuzumab has been termed tumor-associated MUC1 (TA-MUC1)." (PMID 30642093, 2019). "The aberrant tumor-associated form of MUC1 (tMUC1) is predominantly expressed in >80% of human PDA and is a key modulator of several signaling pathways that affect oncogenesis, motility, and metastasis." (PMID 31514488, 2019). "High levels of MUC1 expression and the presence of high concentrations of soluble MUC1 are associated with tumor progression and poor prognosis." (PMID 31468283, 2019). "Since MUC1 expression is associated with tumor aggressiveness, we assessed intratumoral level of MUC1 expression from all treatment groups." (PMID 31693710, 2019). "Utilizing an anti-tumor vaccine based on a synthetically prepared glycopeptide, we generated a monoclonal antibody (mAb) GGSK-1/30, selectively recognizing human tumor-associated MUC1." (PMID 31588183, 2019). "The combination of IHC intensities of CK19 and MUC1 was significantly associated with tumour size, microvascular invasion and satellite nodule formation." (PMID 30875782, 2019). "MUC1 is one of the best-studied tumour-associated antigens, and is abnormally expressed in several malignant conditions." (PMID 31514468, 2019). "Levels of nine MUC1 variants mRNA expression were assessed in tumor and corresponding normal margins in ESCC patients." (PMID 31470870, 2019). "It has been reported that in OEC, autologous DCs loaded with ovarian-associated antigens (ErbB2, MUC-1, and CA-125) were able to stimulate the proliferation of autologous T cells and to induce tumor-specific cytotoxic activity." (PMID 31886313, 2019). "Previously, we demonstrated the potential of TAB004, a monoclonal antibody targeting the unique tumor-associated form of MUC1 (tMUC1) in the early detection of PDA." (PMID 31114758, 2019). "A monoclonal antibody generated from the immunization, exclusively bound to tumor-associated MUC1, allowing for the discrimination of human pancreatic cancer." (PMID 31696111, 2019). "This tumor-associated MUC1 is a marker of an aggressive phenotype, and serves as a tumor neoantigen for targeted immunotherapy." (PMID 31178870, 2019). "We have developed a second generation CAR T cell using the variable fragments of a novel monoclonal antibody, TAB004, which specifically binds the tumor-associated-MUC1 (tMUC1)." (PMID 31514488, 2019). "The thiolated-muc1 aptamer was linked to the gold nanoparticle, via sulfur–gold linkage, to facilitate targeted treatment of the tumor cells." (PMID 31861277, 2019). "In contrast to most other MUC1 antibodies, TAB004 distinguishes between normal and tumor-associated forms of MUC1 by relying solely on the expression of hypo-glycosylated MUC1." (PMID 31114758, 2019). "This suggests that despite the poor immune response against MUC1 detected in most patients, an immune response against this tumor associated antigen has been primed and resulted in the infiltration of activated CTL at the tumor site." (PMID 31214178, 2019). "In two patients who progressed after DC vaccination, loss of MUC1 expression by the tumor was observed." (PMID 31727154, 2019). "Generally, it was shown that MUC1/C, D, and Z splice variants were correlated with tumor progression in ESCC." (PMID 31470870, 2019). "It has been shown that the vaccination with tumor-associated MUC1 tandem repeat peptide in combination with LeIF induced proliferative T cell responses and expression of IFN-γ by CD4+ peripheral blood and lymph node T cells in immunized chimpanzees." (PMID 31183394, 2019).
tumor (continued). "Binding of MUC1-sT to Siglec-9 on macrophages induces a tumor-associated macrophage (TAM) phenotype, that inhibits CD8+ T cell proliferation and results in the upregulation of IDO, CD163 and PD-L1 in-vivo." (PMID 30581432, 2018). "Tumor-associated MUC1 is characterized by altered glycosylation such as hypoglycosylation and increased sialylation relative to that of MUC1 on some normal epithelial cells where it serves a barrier function." (PMID 29796189, 2018). "TAB 004 is an antibody developed to target tumor-associated MUC1 (tMUC1), an antigen that is present at high levels in the serum of cancer patients, including pancreatic and breast cancer." (PMID 29651637, 2018). "MUC1 is overexpressed in 75–90% of human EOC and, interestingly, tumor-associated MUC1 is more immunogenic because of the loss of glycosylation, revealing epitopes that can be targeted by antibodies and specific CD8+ T cell responses." (PMID 30049987, 2018). "The MUC1-sT can interact with Siglec-9 on monocytes and thereby induce secretion of IL-6, M-CSF and chemokines associated with tumor progression." (PMID 30581432, 2018). "The adenovirus (Ad-siSSF) delivers two tumor-associated antigens (TAAs), survivin and MUC1; secretory bacterial flagellin for DC maturation; and an RNA interference moiety to suppress SOCS1." (PMID 29415891, 2018). "We generated cell lines from these KCM mice (KCM cells) and developed a novel monoclonal antibody, TAB004 (OncoTAb, Inc., Charlotte, NC), which specifically targets the hypoglycosylated/tumor-associated form of MUC1 (tMUC1)." (PMID 29462213, 2018). "This also applies to the mechanisms reported to underlie the induction of the PD-L1 ligand by MUC1 in different tumour types." (PMID 29784646, 2018). "MUC-1 has been shown to be a tumor-associated antigen and target molecule for dendritic cell-based immunotherapy in advanced biliary tract cancer." (PMID 30219954, 2018). "In this context, the PANVAC system comprising of recombinant vaccinia and fowlpox viruses, carrying the tumor-associated antigens epithelial MUC-1 and carcinomebryonic antigen (CEA) as well as T cell stimulatory molecules, have been applied." (PMID 29883422, 2018). "A tumour-associated glycoform of MUC1, MUC1-ST can interact with siglec-9 expressed by monocytes and macrophages, resulting in the secretion of many factors that are involved in tumour progression and immune recruitment." (PMID 29903935, 2018). "In our previous studies, AOM/DSS treatment of MUC1.Tg mice resulted in greater weight loss, increased colon shortening and increased tumor incidence compared to WT mice." (PMID 29285251, 2017). "A critical role of MUC1 in this chemoresistance was evidenced by the finding that MUC1 depletion was not only associated with reduction of tumor growth, but also with a complete prevention of tumor relapse after ending PTX treatment." (PMID 28796259, 2017). "We also compared the diagnostic capability of WFA-sialylated MUC1 with that of conventional tumor markers and biliary cytology." (PMID 27358229, 2017). "While it has been repeatedly identified as a major tumor-associated antigen, MUC1-targeting cancer vaccines have met with limited success in terms of patients’ benefit." (PMID 28679396, 2017). "Tumor-associated MUC1 (tMUC1) is a marker of an aggressive phenotype that is cleaved from epithelial cells and released into circulation, allowing detection in the serum." (PMID 28680538, 2017). "Standard chemotherapy (CT) on its own also triggered the development of immune responses against MUC1 and other tested tumor associated antigens including predicted neo-epitopes." (PMID 28923084, 2017). "It remains challenging to produce decisive vaccines against MUC1, a tumor-associated antigen widely expressed by pancreas, breast and other tumors." (PMID 26788922, 2016). "We purified, cloned, and characterized 13 IgGs specific for several tumor-associated MUC1 epitopes with a wide range of binding affinities." (PMID 27545199, 2016).